LAMP2 (lysosome associated membrane protein 2)
Diseases named in the same sentence as LAMP2 in open-access papers (continued):
Sharing a sentence is not in itself a finding about the gene and the disease.
infection (continued). "In contrast, at 1 and 24 h post infection, R. montanensis in Vero cells appear intact with very few bacteria co-localizing with LAMP-2 positive compartments." (PMID 27525249, 2016). "Another ANCA developing in infections is an autoantibody against human lysosome-mediated membrane protein-2 (LAMP-2)." (PMID 24959541, 2013). "Macrophage activation during infection is associated with phagosome maturation, as indicated by the acquisition of RAB7 and LAMP2 on the organelle surface." (PMID 21949656, 2011). "Congruently, overexpression of SphK-1 conferred resistance in macrophages to infection which was due to enhancement in the generation of NO and expression of iNOs, pp38 and LAMP-2." (PMID 20498849, 2010). "Conversely and expectedly, SphK-1 overexpression conferred resistance to infection and enhanced expression of iNOS, pp38 and LAMP-2 proteins in Sphk-1++ macrophages." (PMID 20498849, 2010). "At 2 h after infection, only 26% of the WT strain-containing phagosomes co-localized with the late endosomal/lysosomal marker LAMP-2, while 71% of the iglC mutant-containing phagosomes showed persistent co-localization with the LAMP-2 marker." (PMID 20552012, 2010). "At 30 min after infection, ∼65% of the iglC mutant-containing phagosomes co-localized with LAMP-2 and cathepsin-D, as previously shown." (PMID 20552012, 2010). "We examined co-localization of the phagosomes with the late endosomal/lysosomal marker LAMP-2 and the lysosomal marker cathepsin D at 30 min and 2 h after infection." (PMID 20552012, 2010). "We again found that GAS was initially located in phagosomes, as indicated by EEA-1 staining, which was followed by rapid bacterial colocalization with the mature lysosomal marker LAMP-2 within the first 15 min of infection, similar to the colocalization dynamics observed with LAMP-1 staining." (PMID 38722166, 2024). "Previous work in J774 macrophages showed that infection with live MAP results in reduced acquisition of late endosomal marker LAMP-2, inhibited phagosome-lysosome fusion, and higher pH values for MAP-containing compartments compared to those with dead MAP or non-pathogenic mycobacteria." (PMID 36816182, 2023). "LAMP2 or SURF4 were also up-regulated in ECFCs in response to the serum of critical patients as well as in ECFCs with PCR+ serum (at the highest peak of infection) and, interestingly, in individuals that had overcome the infection without apparent symptoms (PCR-/IgG+)." (PMID 37063416, 2023). "We observed that all glial cells (OECs, TgSCs and astrocytes) showed well-defined LAMP2-positive lysosomes around both WT and ΔcpsE S. agalactiae demonstrating that the bacteria were internalized or colocalized inside lysosomes after infection." (PMID 35281448, 2022). "At 4 h post-infection, most of the Brucella-containing vacuoles (BCVs) were LAMP-2+." (PMID 29963502, 2018). "In contrast, infection with the Lp01ΔankX strain complemented with catalytically inactive AnkXH229A did not rescue the phenotype and showed that 70.6(±7.3)% LCVs were LAMP-2 positive, similar to the percentage observed in cells infected with the Lp01ΔankX or the Lp01ΔdotA strains." (PMID 28944216, 2017). "Both BVs and ODVs entered the cells and 1 h post-infection they were inside LAMP2+ vesicles." (PMID 28033419, 2016). "Thus, although the LAMP-2 pathway remains promising, more studies are needed to clarify its role as a mechanism in ANCA-associated disease and as a link between infection and pathogenic ANCA formation." (PMID 24959541, 2013). "The amount of LAMP-1 and LAMP-2 co-localised with phagosomes steadily increased at the 15 minute, 30 minute and two hour time-points post-infection, and reached a maximum between two and four hours after infection." (PMID 21426584, 2011).
infection (continued). "Enhanced expression of LAMP-2, pp38 and iNOs proteins in SphK-1 ++ infected macrophages over WT infected macrophages demonstrated the increased antimycobacterial response of Sphk-1++ macrophages, which rendered them resistant to the infection." (PMID 20498849, 2010). "The exogenously expressed LAPTM5 was localized to vesicles and exhibited a punctuate pattern, and the LAPTM5-positive vesicles did not colocalize with the Golgi apparatus, but partially colocalized with LAMP2-positive lysosomes 1 day after the infection with Ad-LAPTM5." (PMID 19787053, 2009). "Moreover, we also found the expression level of lysosome-associated membrane protein 2 (Lamp2) was not increased after GCRV-II infection." (PMID 40172227, 2025). "Increased expression of LAMP-2, iNOs and p-p38 in SphK-1++ macrophages in response to M. smegmatis infection suggested increased antimycobacterial potential of Sphk-1++ macrophages, providing the most probable evidence of increased resistance of these macrophages to infection." (PMID 20498849, 2010). "ASFV particles colocalized with SQSTM1/p62 and LAMP2, indicating that ASFV virions entered the autolysosomes during the early phase of infection." (PMID 39688418, 2025). "Overall, these findings demonstrated that the sialidase activity of the HN protein is crucial for the deglycosylation and degradation of LAMP1 and LAMP2, ultimately leading to cellular LMP and apoptosis during the infection of diverse NDV strains." (PMID 38354122, 2024). "Although the subcellular localization pattern of pEP153R shows a huge difference between infection and transfection, LAMP1 and LAMP2 still colocalized with pEP153R gathered in viral factories." (PMID 39451547, 2024). "Secondly, the activation of trafficking regulators LAMP1, LAMP2, and lysosomal enzyme GLA at the transcriptional level activated immune responses, weakening the B. abortus growth at 4 h post-infection (pi)." (PMID 35631117, 2022). "NPC1 shRNA, Lamp2 shRNA and scrambled (SCR) shRNA Vero cells were infected with recombinant fluorescent virus (B54GFP), which expresses GFP as a fusion of the major infection protein p54, at a MOI 1 pfu/ml to infect cells." (PMID 35081156, 2022). "During M. tuberculosis H37Rv infection, a similar colocalization of MCVs with both LC3 and LAMP2 was observed in THP1 and hBMEC cells." (PMID 34402643, 2021). "The presence of LAMP2 around the CCV and fluorescent DQ-Red BSA inside the CCV was prominent at 24 h post-infection in HeLa cells infected with wild-type C. burnetii." (PMID 33282747, 2020). "At 24 h post-infection, vimentin recruitment to the CCV was visible, as judged by co-localization with LAMP2." (PMID 33282747, 2020). "At 2 h post-infection, macrophages were fixed, immunostained with an antibody against the lysosomal marker LAMP-2, and quantified with regard to the number of LAMP-2 positive LCVs." (PMID 28944216, 2017). "A positive feedback loop may thus be formed during the infection process: infection leads to deglycosylation of LAMP1 and LAMP2 and subsequent lysosomal dysfunction, while lysosomal dysfunction further enhances viral entry into the cell." (PMID 38057804, 2023). "Endocytosis-related proteins CD44, Rab5, Rab7, and LAMP2 were increased after infection, while the level of Cathepsin L did not change." (PMID 34163451, 2021). "Other authors also showed that inhibition of endocytosis processes, when cells are treated with the dynamin inhibitor, dynasore or in the case of LAMP-2 lacking cells where caveolin-dependent endocytosis is impaired, leads to a reduction on the infection." (PMID 33194787, 2020). "In macrophages fixed after 48 h of infection, the immunostaining for the PV membrane components LAMP1 and LAMP2 indicates that L. major PVs containing two or three amastigotes (some of them undergoing binary division) may be observed." (PMID 22348167, 2012).
infection (continued). "In untreated rabbits, most of these genes were progressively induced by Mtb infection from 4 to 8 weeks, and many had reached a plateau (IFN-γ, IL13, IL6, MIF, CCL4, NFκB, APRIL, TLR2, RAB7 and LAMP2) or were even reduced (IL10, CXCR3, GMCSF and PI3K3) by 12 weeks post-infection." (PMID 21949656, 2011). "The results showed that at 12–24 h of infection the % of co-localization of the WT FCPs with both LAMP-2 and cathepsin-D positive compartments did not change from the 2 h time point in the CDC27, USP22, or PI4KCA RNAi-treated cells." (PMID 20552012, 2010). "We observed a significant decrease in the number of mycobacterial phagosomes positive for LAMP-2 in bone marrow macrophages (BMM) from Sort1−/− mice compared to mycobacterial phagosomes in Sort1+/+ BMM (Mean = 450.5 ± 47.29 vs. 303.4 ± 31.83, respectively) after 2 h of infection." (PMID 27389464, 2016). "R. montanensis in THP-1-derived macrophages at 1 h post-infection do not appear as intact bacteria and at 24 h post-infection, most of the Rickettsia-positive staining results from debris that partially localizes to LAMP-2 positive compartments." (PMID 27525249, 2016). "However, we also noticed that a portion of Rab32-positive phagosomes are free of late endosomal markers (LAMP1 and LAMP2) and late endosomal/lysosomal probe (Lysotracker) from 1 to 6 h after infection, suggesting that not all Rab32-positive phagosomes are fused with late endosomes." (PMID 31199852, 2019). "A leading candidate, Lamp2, is not likely to play such a role: it did not emerge in the screen for pro-LASV factors, did not rescue infection in Lamp1 KO cells, and does not appear to physically interact with LASV GPC." (PMID 29295909, 2018). "At time zero after infection, LAMP-1 and LAMP-2 showed little or no co-localisation with phagosomes." (PMID 21426584, 2011). "Four days after the infection, LAPTM5-positive vesicles were remarkably accumulated as larger entities in dying cells and colocalized with neither the Golgi apparatus nor LAMP2-positive lysosomes." (PMID 19787053, 2009). "As a control, either at 60 min or 24 h post infection in THP-1 or Vero cells, R. conorii maintain the morphology of intact bacteria, with no significant co-staining with LAMP-2 positive structures, and proliferate within these two cell types as depicted in an increase in rickettsial cells." (PMID 27525249, 2016). "Despite any potential issues with marker specificity, neither our lysosomal markers (LysoTracker, Lamp-1, and Lamp-2), nor our trans-Golgi marker, WGA, indicated co-localization with anti-V Ab after 30–45 min of infection as was observed with our M6P and rab7 Abs." (PMID 19609450, 2009).
tumor (59 papers, 2010 to 2026). "Lysosomal-associated membrane protein 1 (LAMP-1) and Lysosomal-associated membrane protein 2 (LAMP-2), for instance, are highly glycosylated proteins that are often overexpressed on the surface of invasive tumor cells." (PMID 41373734, 2025). "Previous studies have shown increased expression of LAMP2 (lysosomal-associated membrane protein 2 A) in tumor tissues, reflecting a link with acid adaptation." (PMID 40551171, 2025). "We found the expression of LDHA and LAMP2 was highly elevated in the tumor regions and positively associated with a poor clinical stage of CRC." (PMID 38136340, 2023). "Tumor-associated macrophages were investigated by determining the Mac3 (CD107b/LAMP2) immunoreactive area." (PMID 33808256, 2021). "It has been suggested that the antitumor effects of PFT-μ are mediated via inhibition of an interaction of HSP70 with lysosome-associated membrane protein 2, leading to dysregulation of autophagy and enhanced tumor cell death." (PMID 28458631, 2017). "This process may be achieved by affecting the expression and function of lysosomal membrane-associated protein LAMP2, which can affect the autophagy process and tumor microenvironment." (PMID 37986192, 2023). "LAMP2 is a lysosome-related membrane glycoprotein that has been associated with BC tumor cells." (PMID 36519745, 2022). "Several lines of evidence associate enhanced levels of LAMP2 with tumor progression." (PMID 27627761, 2016). "Knock down of Beclin1, ATG5 or LAMP2 reduced autophagosome and autolysosome formation, and tumor cell killing." (PMID 41954991, 2026). "As CRC cells progressed, as indicated by KRAS expression, the expression of tumor acidosis markers (LAMP2, GLUT1, and LDHA), as well as dysadherin, also increased." (PMID 41535258, 2026). "ERRα inhibition impaired the transcriptional expression of LAMP2 and VAMP8 and blocked the fusion of autophagosomes with lysosomes, causing the impairment of the autophagy-lysosome pathway and tumor repression in RCC." (PMID 39820331, 2025). "IHC results confirmed that inhibition of ERRα acetylation repressed the expression of Ki67 in tumor tissues, the expression of LAMP2 and VAMP8 were also inhibited by XCT-790 and CBP-30." (PMID 39820331, 2025). "MRI-CEST tumor pH imaging revealed increased extracellular tumor acidity in 4T1 tumors, along with marked spatial intratumoral heterogeneity, in contrast to the more homogenous 67NR tumors, as further confirmed by LAMP-2 staining." (PMID 40551171, 2025). "Quantitative image analysis confirmed a significant reduction in the tumor-to-liver ratio of LAMP-2 staining in treated mice compared to untreated (mean ± SD: 1.53 ± 0.27 vs 6.285 ± 0.21; p = < 0.0001)." (PMID 41377976, 2025). "We found significantly higher numbers of B220+ and Mac3/LAMP-2+ in LysM-Cre:Hmox1flfl mice correlating with smaller tumors, suggesting a pronounced immune responses in the tumor microenvironment." (PMID 35565370, 2022). "We then considered V-ATPase and LAMP2 expression as indirect markers of acidifying tumor cells and acidified tumor area." (PMID 34124067, 2021). "LAMP2 and HSP90α were also highly expressed in the tumor internal hypoxia area compared to the normoxia tumor area in vivo; however, the expression of MLKL was decreased in hypoxia." (PMID 33440739, 2021). "By overlaying the acidity map created by Seminaphtolrhodafluor-1 vis IHC staining of LAMP2 in the tumor, the region where LAMP2 is overexpressed is matched with the acidic region." (PMID 34158625, 2021). "Lamp2 has been described to be overexpressed in aggressive tumors and to be upregulated in acidosis-adapted tumor cells." (PMID 33407762, 2021). "LAMP2 has been functionally validated as an essential mediator of drug resistance and tumor recurrence in hematological diseases." (PMID 33692952, 2021).
tumor (continued). "We detected LAMP2 expression in isolated mouse tumors and found that host cell knockout of Ogr1 reduced LAMP2 expression in tumors, suggesting that the phenomenon of tumor acidosis was somewhat buffered." (PMID 34158625, 2021). "LAMP2 is essential for maintaining the structural integrity of the lysosomal compartment and relocalizes to the cell surface of some highly metastatic tumor cells." (PMID 33692952, 2021). "The expression levels of FAM215A and LAMP2 were decreased in the tumor tissues with FAM215A-knockdown cell-derived tumors compared to mice injected with control cells." (PMID 32295144, 2020). "In conclusion, we herein show for the first time that the lncRNA, FAM215A, is highly expressed in HCC, where it interacts with and prevents the ubiquitination of LAMP2 to increase tumor progression and decrease doxorubicin sensitivity." (PMID 32295144, 2020). "Our results therefore collectively suggest that FAM215A induces tumor progression, metastasis, and doxorubicin resistance, potentially through LAMP2." (PMID 32295144, 2020). "In previous studies, LAMP2 was shown to act as an oncogene, to be required for tumor growth, and to promote tumor recurrence." (PMID 32295144, 2020). "Together, our results show that the lncRNA, FAM215A, is highly expressed in HCC, where it interacts with and stabilizes LAMP2 to increase tumor progression while decreasing doxorubicin sensitivity." (PMID 32295144, 2020). "Our tissue IHC staining data demonstrate that LAMP1 and LAMP2 expression is highly positive at the apical site of tumor cells." (PMID 31425520, 2019). "Later, the authors measured the in vivo tumor pH and concluded that LAMP2 enhanced expression and plasma membrane localization highlights the regions of progressive tumor acidosis." (PMID 28299282, 2017). "Results from four mice demonstrate that LAMP2 staining was diffuse in primary tumour regions (Figure 8ai and aii), as expected for the protein’s normal lysosomal targeting." (PMID 28368405, 2017). "Lysosome associated membrane glycoprotein 1 (LAMP1) and Lysosome associated membrane glycoprotein 2 (LAMP2), which implicates in tumor cell metastasis, were identified with 12 and 9 N-glycosites separately." (PMID 28077793, 2017). "This adaptation is proposed to prevent the cell membranes from acid hydrolysis, which is akin to mechanism suggested for LAMP2 function in the acid-adapted tumor cells." (PMID 28299282, 2017). "Lysosomal processes were important to plastic sub-populations in cell lines, so we stained tumour fractions for the lysosome marker LAMP-2." (PMID 26981578, 2016). "The percent of LAMP2-positive pixels in ZR-75.1 bicarbonate-treated tumours was significantly (Student's t-test; P<0.05) less compared with the tumours in tap-water-treated animals." (PMID 26658462, 2015). "These analyses showed that LAMP2 expression was significantly higher in more acidic areas of the tumour." (PMID 26658462, 2015). "High LAMP2 staining was seen at the interface of necrotic areas with areas of fully viable cells and invasive edges of tumours." (PMID 26658462, 2015). "Staining whole-mount tumour samples for LAMP2 revealed that it is localized at the tumour–stromal interface and peri-luminal regions of DCIS, which are expected to be acidic." (PMID 26658462, 2015). "The expression of LAMP2 protein showed statistically (P<0.0001) higher levels in tumour samples, compared with normal breast." (PMID 26658462, 2015). "Our results showed that LAMP2 knockdown tumours were less active and smaller at the early stages, similar to the caliper data for tumour size." (PMID 26658462, 2015). "We observed that the tumour size was smaller in the LAMP2 knockdown group in the initial phase of tumour growth (day 1–7)." (PMID 26658462, 2015). "In this study, the authors show that malignant cells adapt to the acidic tumour microenvironment by redirecting LAMP2 from lysosomes to the plasma membrane." (PMID 26658462, 2015).